MIR1302-9HG (MIR1302-9 host gene)
Gene: Long non-coding RNA gene on chromosome 9 (27,657 to 30,893, forward strand). Ensembl gene ENSG00000227518.
Gene Ontology:
Biological process: miRNA-mediated post-transcriptional gene silencing